KISS1R (KISS1 receptor)
Diseases named in the same sentence as KISS1R in open-access papers (continued):
Sharing a sentence is not in itself a finding about the gene and the disease.
triple-negative breast carcinoma (6 papers, 2017 to 2026). An invasive breast carcinoma which is negative for expression of estrogen receptor (ER), progesterone receptor (PR), and human epidermal growth factor receptor 2 (HER2). "In KISS1R overexpressing triple-negative breast cancer (TNBC) cells, stimulation has been associated with increased invasion and MMP-9 expression, leading to the suggestion that hormone receptor status determines the metastatic effects of kisspeptin." (PMID 35955878, 2022). "Kisspeptins (KPs) and their receptor (KISS1R) promote metastasis and tumor progression in various cancers such as triple-negative breast cancer (TNBC)." (PMID 41774810, 2026). "Furthermore, overexpression of KiSS-1R has been reported to elicit drug resistance in triple negative breast cancer." (PMID 29760678, 2018). "Our earlier work has shown that, in triple-negative breast cancer (TNBC), KISS1R signaling promotes tumor growth and metastasis." (PMID 35349482, 2022).
endometriosis (5 papers, 2017 to 2025). The growth of functional endometrial tissue in anatomic sites outside the uterine body. "Research indicates that women with endometriosis exhibit altered levels of kisspeptin and its receptor, KISS1R, particularly in eutopic and ectopic endometrial tissues, compared to healthy controls." (PMID 39768606, 2024). "Research indicates that women with endometriosis exhibit altered levels of kisspeptin and its receptor, KISS1R, in both eutopic and ectopic endometrial tissues, suggesting a role in disease progression, particularly in tissue invasion and lesion formation." (PMID 39768606, 2024). "There is also evidence for the important role of kisspeptin 1 (KISS1) and its receptor (KISS1R) in the pathogenesis of endometriosis." (PMID 35408850, 2022). "The difference in the expression of KISS1/KISS1R in ectopically implanted endometrial tissue compared to the endometrium of women with and without endometriosis suggests their potential future use as biomarkers for early diagnosis of endometriosis." (PMID 40429279, 2025). "Results indicated lower levels of KISS1 and KISS1R in the eutopic endometrium of patients with endometriosis compared to controls, suggesting that a deficiency in KISS1 and KISS1R may promote tissue invasion and contribute to endometriosis pathogenesis." (PMID 39768606, 2024). "Tissue samples from 35 women with endometriosis and 14 control subjects were tested with KISS1 and KISS1R antibodies." (PMID 39768606, 2024). "A separate study aimed to examine the immunoreactivity of kisspeptin and its receptor, KISS1R, in both eutopic and ectopic endometrial tissues of women with and without endometriosis across the proliferative and secretory phases of the menstrual cycle." (PMID 39768606, 2024). "They demonstrated that KISS1 and KISS1R levels are downregulated in eutopic endometrial stroma from women with endometriosis versus those without the disease." (PMID 35408850, 2022).
ovarian carcinoma (5 papers, 2007 to 2023). A malignant neoplasm originating from the surface ovarian epithelium. "Altogether, these results are indicative of the tumor suppressing nature of Kiss1 and its receptor, Kiss1R, in ovarian cancer." (PMID 28439256, 2017). "Immunohistochemical analysis of 518 ovarian cancer tumor samples suggested a favorable prognostic role of Kiss1R with regards to the total survival duration as well as the disease-free survival period." (PMID 28439256, 2017). "Despite the similarity of Kiss1R expressions levels between malignant and benign ovarian tumors, the expression of Kiss1 was found to be significantly higher in malignant ovarian tumors." (PMID 28439256, 2017). "However, recent evidence suggests that kisspeptin (Kiss1) and Kiss1R are involved in ovarian cancer progression." (PMID 28439256, 2017). "Additionally, high expression levels of Kiss1R decreased the lysophosphatidic acid induced migration of ovarian cancer cells." (PMID 28439256, 2017). "Based on the various ovarian cancer studies, the independent findings propose that KISS1/KISS1R protein levels could be used as prognostic biomarkers of disease progression in ovarian cancer." (PMID 30123188, 2018).
diabetes (4 papers, 2018 to 2025). "In this article, we provide an overview of the KISS1/KISS1R system and its involvement in diseases such as reproductive disorders, cancer, diabetes, and cardiovascular disease." (PMID 40430029, 2025). "Kisspeptin levels are increased in adults with type 2 diabetes mellitus and in mouse models of diabetes, and global KISS1R knockout and knockdown of liver KISS1 in particular improve glucose tolerance." (PMID 40430029, 2025).
Glucose intolerance (4 papers, 2018 to 2024). Glucose intolerance (GI) can be defined as dysglycemia that comprises both prediabetes and diabetes. "In the liver, the deletion of Kiss1r in hepatocytes augments glucose intolerance and insulin resistance in an HFD-fed mouse model of MASLD, in addition to increasing hepatic steatosis and its progression to MASH." (PMID 39404414, 2024). "The currently observed effects of Kp on glucose metabolism appear to be in line with the glucose intolerance observed in Kiss1r KO mice." (PMID 33960524, 2021).
Hepatic steatosis (4 papers, 2022 to 2025). Steatosis is a term used to denote lipid accumulation within hepatocytes. "The peptide hormone kisspeptin, signaling via its receptor, KISS1R, decreases hepatic steatosis and protects against metabolic dysfunction-associated steatotic liver disease (MASLD)." (PMID 40862768, 2025). "Together, these findings suggest that loss of hepatic KISS1R signaling exerts a deleterious effect on the liver by increasing hepatic steatosis and the progression to NASH." (PMID 35349482, 2022). "Using LKO mice, we found that hepatic Kiss1r deficiency dramatically exacerbated hepatic steatosis compared with that in littermate controls fed HFD." (PMID 35349482, 2022). "Hepatic KISS1R deficiency aggravates hepatic steatosis in insulin-resistant obese mice." (PMID 35349482, 2022). "Depletion of hepatic Kiss1r exacerbated hepatic steatosis, while the pharmacological enhancement of KISS1R signaling lowered hepatic triglyceride content, serum triglyceride levels, and serum free fatty acid levels." (PMID 40862768, 2025). "The peptide hormone kisspeptin attenuates liver steatosis, metabolic dysfunction-associated steatohepatitis (MASH), and fibrosis in mouse models by signaling via the kisspeptin 1 receptor (KISS1R)." (PMID 39404414, 2024). "KISS1R agonist alleviates hepatic steatosis and metabolic deterioration in a wild-type mouse model of NAFLD." (PMID 35349482, 2022). "In contrast, activation of hepatic KISS1R using a potent KP agonist (KPA) protected against the development of hepatic steatosis and was found to reduce progression to NASH and hepatic fibrosis." (PMID 35349482, 2022). "In this study, using a high-fat diet–induced (HFD-induced) mouse model of NAFLD, we demonstrate that hepatic knockout of Kiss1r in mice exacerbated liver steatosis." (PMID 35349482, 2022). "Using high-fat diet–fed mice, we demonstrated that a deletion of hepatic Kiss1r exacerbated hepatic steatosis." (PMID 35349482, 2022). "Data show that activation of KISS1R by KPA had a beneficial effect, significantly reducing hepatic steatosis and decreasing NASH progression in mice fed HFD." (PMID 35349482, 2022). "Thus, activation of hepatic AMPK downstream of KISS1R can alleviate DNL by decreasing SREBP-1c levels, thereby decreasing CIDEA and lipogenic genes involved in hepatic steatosis." (PMID 40862768, 2025).
lung carcinoma (4 papers, 2017 to 2026). "However, we also confirmed protein expression in patient specimens for two novel lung cancer targets, i.e. FAT2 and KiSS-1R." (PMID 29371917, 2017).
bladder cancer (3 papers, 2018 to 2022). "For example, an evaluation of KISS1R, SEPT9, and CSAD methylation in bladder cancer improved the AUC for predicting lymph node status (AUC = 0.68–0.72), compared with KISS1R (AUC = 0.67) SEPT9 (AUC = 0.58), or CSAD (AUC = 0.70) alone." (PMID 35992328, 2022).
female infertility (3 papers, 2017 to 2024). Diminished or absent ability of a female to achieve conception. "Dysregulation or naturally occurring mutations of the kisspeptin/KISS1R system may negatively affect the ovarian function, leading to reproductive pathology or female infertility." (PMID 29354093, 2017).
Hepatic fibrosis (3 papers, 2022 to 2025). The presence of excessive fibrous connective tissue in the liver. "Moreover, studies indicate that hepatic KiSS1R deficiency promotes liver fibrosis biomarkers in a high-fat diet (HFD)-induced mouse model." (PMID 37968564, 2023). "Hepatic AMPK activation downstream of KISS1R can also protect against inflammation by inhibiting NF-κΒ signaling and alleviate hepatic fibrosis by decreasing fibrogenic signaling." (PMID 35349482, 2022). "We have recently shown that the activation of KISS1R can decrease fibrosis in patient livers, via the inactivation of transforming growth factor (TGF)b signaling in hepatic stellate cells, the main drivers of hepatic fibrosis." (PMID 40862768, 2025).
hypothyroidism (3 papers, 2022 to 2025). Abnormally low levels of thyroid hormone. "The increase in Kiss1r caused by hypothyroidism may be a compensatory effect of the reduced hypothalamic Gnrh1 expression, although further studies are needed to elucidate this issue." (PMID 37798396, 2023). "In the uterus, hypothyroidism reduced Kp immunostaining on diestrus and KISS1R mRNA levels on proestrus." (PMID 39859259, 2025). "However, it remains unclear whether hypothyroidism influences uterine responses to sex steroids throughout the reproductive cycle and whether these effects are linked to alterations in the local expression of Kiss1 and Kiss1r." (PMID 39859259, 2025). "This study investigated the impact of hypothyroidism on the uterine expression of Kp and Kiss1r in female rats throughout the estrous cycle and the associated changes in uterine activity modulators." (PMID 39859259, 2025). "There was a reduction in the stained area of Kiss1 (**P<0.01) and Kiss1r (***P < 0.001) in rats with hypothyroidism." (PMID 37798396, 2023). "In the present study, we investigated the HPG axis of male rats with hypothyroidism, the testicular expression of the Kiss1/Kiss1r system, and the therapeutic potential of Kp10 in the gonadal dysfunction of these animals." (PMID 37798396, 2023). "Meanwhile, the expression of transcripts for Kiss1r showed a tendency towards a reduction in the testes of rats with hypothyroidism compared to control (P = 0.06)." (PMID 37798396, 2023). "We have recently demonstrated that rats with maternal hypothyroidism, another important gestational disease, also exhibit decidual and placental reduction of the kisspeptin/Kiss1R system." (PMID 35966095, 2022). "Interestingly, hypothyroidism led to a reduction in Kiss1 immunostaining in diestrous rats, primarily in the stroma, and also reduced KISS1R gene expression during proestrus." (PMID 39859259, 2025). "In addition to the macroscopic and histological alterations, hypothyroidism reduced Kiss1 and Kiss1r immunostaining and gene expression in the rat’s testis." (PMID 37798396, 2023). "Since maternal hypothyroidism in rats reduces placental and decidual expression of the Kiss/Kiss1r system, this may also be one of the reasons for the activation of reticular stress in the placenta of these animals." (PMID 35966095, 2022). "However, it is unclear whether hypothyroidism also impacts the uterine expression of the Kiss1/Kiss1r system throughout the estrous/menstrual cycle." (PMID 39859259, 2025). "The findings of the present study describe the inhibitory effects of hypothyroidism on the HPG axis of male rats, with inhibition of the testicular Kiss1/Kiss1r pathway and an increase in hypothalamic Pdyn expression." (PMID 37798396, 2023). "However, there is still no information on whether hypothyroidism can affect the testicular expression of the Kiss1/kiss1r system and whether the treatment with kisspeptin could modulate the expression of this system." (PMID 37798396, 2023).
Impaired glucose tolerance (3 papers, 2019 to 2023). An abnormal resistance to glucose, i.e., a reduction in the ability to maintain glucose levels in the blood stream within normal limits following oral or intravenous administration of glucose. "Namely, global Kiss1r knockout (KO) female mice display increased body weight, adiposity, serum leptin concentration and impaired glucose tolerance when compared to wild type littermates." (PMID 37035685, 2023). "The kisspeptin receptor (Kiss1r) gene knock-out female mice showed greater body weight, adiposity, fasting blood glucose, and the proportion of impaired glucose tolerance, but lower energy expenditure than the controls." (PMID 33224197, 2020). "Furthermore, studies using Kiss1r KO mice have shown that impaired kisspeptin signaling leads to increased body weight, adiposity, and hyperleptinemia in adult female mice, along with decreased energy expenditure and impaired glucose tolerance." (PMID 37035685, 2023).
Insulin resistance (3 papers, 2019 to 2024). Increased resistance towards insulin, that is, diminished effectiveness of insulin in reducing blood glucose levels. "Hepatic KISS1R deficiency promotes insulin resistance, hepatic inflammation, and hepatic fibrosis biomarkers." (PMID 35349482, 2022). "Because selective insulin resistance plays an important role in the pathogenesis of NAFLD, metabolic tests were performed to examine the effect of the loss of hepatic KISS1R on glucose homeostasis." (PMID 35349482, 2022).
metabolic dysfunction-associated steatotic liver disease (3 papers, 2023 to 2025). Metabolic dysfunction-associated steatotic liver disease (MASLD, formerly known as nonalcoholic fatty liver disease or NAFLD) is a type of liver disease that is not caused by alcohol. "Activated KISS1R can prevent inflammation by inhibiting NF-κB signaling in nonalcoholic fatty liver disease." (PMID 40761792, 2025).
myeloma (3 papers, 2016 to 2018). "In fact, KISS1 and KISS1R have been shown to be highly expressed in mesenchymal stem cells in multiple myeloma." (PMID 30046386, 2018). "In the last few years many authors have worked to determine the suitability of KISS1R for myeloma multiplex diagnosis." (PMID 28830484, 2017). "From these studies, the KISS1 receptor (KISS1R), a G-protein-coupled receptor known to play a role in the regulation of endocrine functions, was identified as a target gene that was upregulated on mesenchymal stem cells (MSCs) and osteoprogenitor cells (OPCs) when co-cultured with myeloma cells." (PMID 27158817, 2016). "In addition, physical interaction with myeloma cell lines AMO1 and U266 clearly enhanced expression of KISS1R mRNA in bone-forming cells." (PMID 27158817, 2016).
papillary thyroid cancer (3 papers, 2009 to 2018). "KISS1R is a human metastasis suppressor gene whose product, metastin, has a potential role in modulating the biologic behavior of papillary carcinomas." (PMID 24358304, 2013). "Ringel and co-workers demonstrated that metastin is expressed in normal thyroid and in papillary thyroid carcinomas, while KiSS-1R is overexpressed in papillary thyroid cancer but not in normal thyroid and in follicular adenomas." (PMID 29760678, 2018).
renal cell carcinoma (3 papers, 2015 to 2021). "Honokiol inhibits the migration of renal cell carcinoma through activation of the RhoA/ROCK/MLC signaling pathway and by targeting KISS1/KISS1R signaling." (PMID 34671554, 2021).
Azoospermia (2 papers, 2020 to 2025). Absence of any measurable level of sperm,whereby spermatozoa cannot be observed even after centrifugation of the semen pellet. "Loss‐of‐function mutations of KISS1R cause normosmic idiopathic hypogonadotropic hypogonadism (IHH) which result in azoospermia at the pre‐testicular level." (PMID 31821609, 2020). "Differences between mice with the Gpr54 gene and Kiss1r-/- knockout mice have been reported in several studies, including observations of azoospermia, reduced testosterone levels, and smaller testicular size in male rodents." (PMID 40429279, 2025).
depression (2 papers, 2024 to 2025). "The drug-gene interaction analysis focused on LILRA5, CYP4F2, and KISS1R, which are implicated in the comorbidity of depression and renal failure." (PMID 40595897, 2025). "Notably, LILRA5, CYP4F2, and KISS1R consistently exhibited higher expression levels in the disease groups compared to controls, suggesting their prominent roles in the pathophysiology of depression and chronic nephritis." (PMID 40595897, 2025). "PPI network analysis identified 23 hub genes, including CYP4F2, KCNA3, KISS1R, LILRA5, and ZC3H12D, as key players in the shared pathophysiology of ESRD and depression." (PMID 40595897, 2025). "We discovered that the five key genes CYP4F2, KCNA3, KISS1R, LILRA5 and ZC3H12D remained different after Venn diagram overlap of DEGs across depression and renal failure datasets." (PMID 40595897, 2025). "Further, protein-protein interaction (PPI) network analysis pinpointed five central genes CYP4F2, KCNA3, KISS1R, LILRA5, and ZC3H12D as pivotal players in the shared pathophysiology of depression and renal failure." (PMID 40595897, 2025). "PPI network analysis identified CYP4F2, KCNA3, KISS1R, LILRA5, and ZC3H12D as key players in the shared pathophysiology of ESRD and depression." (PMID 40595897, 2025).
glioblastoma (2 papers, 2009 to 2016). The most malignant astrocytic tumor (WHO grade IV). "In contrast, ZNF395 and KISS1R expression and their hypoxia induction were observed in all four glioblastoma cell-lines, while TNFAIP3 was hypoxia-inducible in LN229 and LNZ308." (PMID 19536297, 2009).
Hypertension (2 papers, 2011 to 2023). The presence of chronic increased pressure in the systemic arterial system. "Alternatively, increases in local perivascular production of kisspeptins could contribute to hypertension and plasma extravasation during pregnancy, but also other disorders in which expression of kisspeptins and Kiss1R increase." (PMID 21347414, 2011). "In contrast, Kiss1R expression was present in all three tissues, but did not increase during hypertension either." (PMID 21347414, 2011).
Miscarriage (2 papers, 2019 to 2023). A pregnancy that ends at a stage in which the fetus is incapable of surviving on its own, defined as the spontaneous loss of a fetus before the 22th week of pregnancy. "However, as discussed in this review, the kisspeptin/KISS1R system plays a direct role in peripheral organs (including the ovary, testis, uterus, and placenta) and is implicated in reproductive diseases such as miscarriage and PCOS." (PMID 31399145, 2019).
premature ovarian failure (2 papers, 2024 to 2025). "Observations in mice with conditional ablation of Kiss1r in oocytes suggest that the resulting deregulation may lead to premature ovarian failure." (PMID 40725450, 2025). "Furthermore, KISS1R haploinsufficiency leads to premature ovarian failure, which is not rescued by ovarian gonadotrophin replacement." (PMID 38665935, 2024).
pyometra (2 papers, 2023 to 2024). "Studies evaluating kisspeptin and its receptor Kiss1r in cases of feline and canine pyometra are limited, although some have demonstrated the immunomodulatory role of kisspeptin in other reproductive diseases in mice." (PMID 39457917, 2024). "Furthermore, this study showed a positive correlation between the expression of genes KISS1 and KISS1R in the uterus of cats and reported that the pyometra, a major uterine inflammatory disease in female cats, increases endometrial protein expression of Kiss1 and Kiss1r." (PMID 37835759, 2023).
thyroid cancer (2 papers, 2017 to 2023). "In rat luteal and thyroid cancer cells, kisspeptin cannot stimulate the phosphorylation of PI3K/Akt, whereas kisspeptin induced the phosphorylation of PI3K/Akt in stably KISS1R-overexpressed thyroid cancer cells." (PMID 29354093, 2017).